TWIST1 (twist family bHLH transcription factor 1)
Diseases named in the same sentence as TWIST1 in open-access papers (continued):
Sharing a sentence is not in itself a finding about the gene and the disease.
breast carcinoma (continued). "In 19/100(19%) breast cancer samples tested, TWIST1 was overexpressed, while in 15/100(15%) samples the CD24−/low/CD44high profile, and in 9/100(9%) the CD24−/low/ALDH1high profile was detected." (PMID 31261917, 2019). "Our study implied that RBMS3-mediated decrease in Twist1 expression played a crucial role in the breast cancer metastasis process." (PMID 30819235, 2019). "Collectively, analysis of publicly available data further supports the association and likely involvement of TBX3, along with downstream EMT transcription factors SLUG and TWIST1, in the aggressiveness of low‐grade breast cancers." (PMID 30697731, 2019). "Among them, SRC-1 serves as a coactivator for transcription factor PEA3 to enhance Twist1 expression, indicating that SRC-1 promotes breast cancer invasiveness and metastasis by upregulating Twist1 expression." (PMID 30973923, 2019). "In breast cancer cells, IL-6 dramatically induced the expression of TWIST1 and SNAIL1 via STAT3 activation, leading to the initiation of an EMT." (PMID 31123345, 2019). "Adipocytes induce EMT in breast cancer cells by increasing, among some other factors, the expression of TWIST1." (PMID 31331001, 2019). "MicroRNA-34a protects against breast cancer proliferation, invasion and metastasis by directly targeting TWIST1." (PMID 31331001, 2019). "Along with TGF-β/SMAD3 signaling, upregulation of transcription factors SLUG and TWIST1 plays an important role in EMT in this breast cancer subtype." (PMID 31075939, 2019). "For example, signal transducer and activator of transcription 3 binds directly to the human Twist1 promoter and activates its transcriptional activity in human breast cancer, hepatocellular carcinoma, and gastric cancer cell lines." (PMID 31383001, 2019). "In another study, a TWIST1-specific siRNA was delivered in ovarian and breast cancer cells by polyamidoamine dendrimers (PAMAM) and hyaluronic acid conjugated mesoporous silica nanoparticles (MSN-HAs)." (PMID 31861725, 2019). "Our results revealed that melatonin modulated multiple changes induced by doxorubicin, and we found, for the first time, that melatonin counteracted the stimulatory effect of doxorubicin on the expression of TWIST1 in breast cancer cells." (PMID 31331001, 2019). "The main limitation of our study is that we examined the expression of only one EMT marker, TWIST1 in the EpCAM+ cells of early breast cancer patients." (PMID 31261917, 2019). "Twist1 is aberrantly expressed in many types of aggressive tumors, including breast cancer, hepatocellular carcinoma, prostate cancer, gastric cancer, bladder cancer, pancreatic cancer, oesophageal squamous cell carcinoma and gliomas." (PMID 30973923, 2019). "For instance, epigenetic activation of twist family bHLH transcription factor 1 (TWIST1) by metadherin (MTDH) promotes cancer stem-like cell traits in breast cancer." (PMID 30231942, 2018). "The diagnostic efficacy of lncATB (AUC = 0.851, P < 0.001) and Twist1 (AUC = 0.778, P = 0.001) in breast cancer patients was evaluated by calculating the area under the receiver operating characteristic (ROC) curve." (PMID 30518916, 2018). "In another study, Twist1 expression in breast cancer patients correlated with early distant relapse." (PMID 29681769, 2018). "In our study, we have further analysed the survival of both lncATB and Twist1 in breast cancer patients." (PMID 30518916, 2018). "In the xenograft tumor model of breast cancer, ectopic expression of IL-6 can significantly increase the infiltration of Twist1-positive CAFs, and Twist1 is necessary and sufficient for the trans-differentiation formation of CAFs." (PMID 30175384, 2018). "Recently, Li CW have found inhibition of Akt1 using MK-2206 induced epithelial-to-mesenchymal transition through blocking Twist1 degradation in breast cancer." (PMID 30445978, 2018).
breast carcinoma (continued). "Since we found that the sponging of miR-200c by lncATB restored the expression of Twist1 in breast cancer cell lines, we also investigated the correlation between the clinicopathological characteristics and Twist1 expression levels in breast cancer patients." (PMID 30518916, 2018). "Intriguingly, Twist1 was another most significantly activated transcriptional factors by lncATB overexpression among those evaluated in breast cancers." (PMID 30518916, 2018). "In this regard, CT45A1 is a potent inducer of the expression of the EMT master gene Twist1 in breast cancer and thereby promotes tumor invasion, and metastasis." (PMID 29361914, 2018). "In conclusion, we have described the important regulatory roles played by the lncATB/miR200c/Twist1 axe in breast cancer carcinogenesis and progression." (PMID 30518916, 2018). "A recent study showed that POU2F1 regulates expression of the EMT genes Twist1, Snai1 and Snai2 under hypoxia-dependent loss of PER2 in breast cancer." (PMID 28489585, 2017). "Like in breast cancer cells, in SiHa and CaSki cervical cancer cell lines, we also found by luciferase assay that Twist1 promoter activity and expression were decreased by TQ." (PMID 29207526, 2017). "Twist1 over-expression is commonly observed in breast cancer, bladder cancer, gastric cancer, hepatocellular carcinoma, esophageal squamous cell carcinoma, nasopharyngeal carcinoma, head and neck cancer (HNC), glioblastoma, and chronic myelogenous leukemia." (PMID 28099910, 2017). "Knockdown of TWIST1 expression in mammary carcinoma 4T1 cells suppressed the ability of 4T1 cells to metastasize from the mammary gland to the lung mice." (PMID 28085222, 2017). "We found strong positive correlations between SIX1, SNAI1 or TWIST1 with GLI1 (a Hh pathway target) in numerous breast cancer data sets." (PMID 28604738, 2017). "We found that wogonoside reduced the mRNA and protein expression of Twist1 in TNF-α-induced MDA-MB-231 and MDA-MB-435 cells, which indicated that the anti-metastatic effect of wogonoside in breast cancer was dependent of Twist1 expression." (PMID 28774312, 2017). "A recent meta‐analysis showed a positive correlation between expression of EMT‐TFs (SNAIL1, SNAIL2, and TWIST1) and 3‐year overall survival in 3218 patients with advanced breast cancer (HR 1.72, 95% CI = 1.53–1.93)." (PMID 28085222, 2017). "The propensity of breast cancer for metastatic dissemination is positively related to expression of Epithelial–Mesenchymal Transition (EMT) markers such as Twist1 and Vimentin, and negatively related to expression of adhesion markers such as E-Cadherin." (PMID 28978097, 2017). "Twist1 promoter contains a functional p65-binding motif, several lines of evidence show that TNF-α-mediated Twist1 expression in breast cancer cells contributes to their aggressive phenotype." (PMID 28774312, 2017). "BMI-1 was shown to be essential in the regulation of SNAIL expression in breast cancer and TWIST1 expression in head and neck cancer." (PMID 28968963, 2017). "It has been known that TNF-α promotes EMT by up-regulating transcription factors such as Twist1/2, Snai1/2 and Zeb1/2 in renal cell carcinoma, breast cancer cell and colon cancer cell." (PMID 28550311, 2017). "Our previous study reported that TQ inhibits metastasis via downregulation of Twist1 and upregulation of E-Cadherin in metastatic breast cancer cell lines." (PMID 29207526, 2017). "We found that the mean transcript expression of VIM, CDH2, FN1, and TWIST1 were higher in the basal B breast cancer cells with low FRK transcript levels as compared to Basal A and Luminal cells that harbor high FRK transcript levels (P<0.05)." (PMID 29348886, 2017). "A subsequent study further confirmed that STAT3 directly binds to the second proximal STAT-3-binding site on the human Twist1 promoter and activates its transcriptional activity in human breast cancer cell lines." (PMID 28099910, 2017).
breast carcinoma (continued). "Over-expression of Twist1 in breast cancer increases vascular endothelial growth factor (VEGF) expression and induces angiogenesis in vivo." (PMID 28099910, 2017). "a novel EMT-suppressing transcription factor in basal-like breast cancer (BLBC), FOXF2 deficiency enhances metastatic ability of BLBC cells by activating the EMT program through upregulating the transcription of TWIST1." (PMID 28121627, 2017). "Evidence from basal-like breast cancer (BLBC) cells demonstrated that Twist1 can be diacetylated at K73 and K76 by Tip60." (PMID 28099910, 2017). "In pancreatic cancer cell lines, HGF/c-Met has been showed to transmit intracellular signal via MAPK pathway, and is essential to phosphorylate and stabilize TWIST1 in breast cancer." (PMID 27280289, 2016). "We unexpectedly noticed that in 4T1 mouse breast cancer cells ectopically expressed TRIM28 is capable of enhancing the protein level of Twist1 and meanwhile repressing its mRNA level." (PMID 27412325, 2016). "CDH2 (encoding N-cadherin), VIM (encoding vimentin), TWIST1/2 (products which are EMT transcriptional factors) and SNAI1, as well as ZEB1, are well known key players involved in EMT-like processes of breast cancers." (PMID 27617643, 2016). "Identification of the TRIM28-TWIST1-EMT axis in breast cancer cells makes TWIST1 a potential therapeutic target for breast cancer treatment." (PMID 27412325, 2016). "This was expanded upon by a group that isolated DTCs from the bone marrow of breast cancer patients and using a PCR based assay found an upregulation of the E-cadherin transcriptional repressor TWIST1." (PMID 27189371, 2016). "On the other hand, the levels of the mesenchymal markers N-cadherin, Twist1 and vimentin were 2.3, 12 and 3 fold higher in breast cancer cells treated with SFCM from TCF-169-CHEK2-siRNA as compared to SFCM from control cells." (PMID 27484185, 2016). "Very few studies revealed that TWIST1 promoted endothelium-dependent angiogenesis in breast cancer and in hepatocellular carcinoma by recruiting macrophages, altering metalloproteinase 9 expression, and activating of VEGF-A signaling." (PMID 27280289, 2016). "In the same line of evidence, suppression of Twist (Twist1 gene) in highly metastatic mammary carcinoma cells inhibits their ability to move from the mammary gland to the lung." (PMID 26985909, 2016). "Both Twist1 and Twist2 are overexpressed in breast cancer cells exhibiting a stem-like phenotype (CD44high/CD24low)." (PMID 27023622, 2016). "It has been also reported that ARTN confers chemo- and radio-resistance upon mammary carcinoma cells by promoting TWIST1-BCL-2-dependent CSC-like behavior." (PMID 26675549, 2016). "Upon metastatic dissemination in recipient mice, the metastatic breast cancer cells require ID1 to inactivate the transcriptional activity of Twist1 before MET can occur." (PMID 27367735, 2016). "In the present study, we found that ectopic expression of miR-151 represses cell migration and invasion of breast cancer cells by down-regulating TWIST1." (PMID 27930738, 2016). "In this study, we explored the potential role of miR-151 in TWIST1 expression and cancer properties in human breast cancer cells." (PMID 27930738, 2016). "The results further confirmed the role of miR-151-3p in regulating TWIST1 expression in human breast cancer cells." (PMID 27930738, 2016). "We find that TRIM28 is highly expressed in both cancer cell lines and advanced breast cancer tissues, and the levels of TRIM28 and TWIST1 are positively correlated with the aggressiveness of breast carcinomas." (PMID 27412325, 2016). "Our findings add to accumulating evidence that microRNAs are involved in breast cancer progression by modulating TWIST1 expression." (PMID 27930738, 2016). "Twist1 was detected in a small subset (1%) of patients with breast cancer, in circulating tumor cells." (PMID 26797644, 2016).
breast carcinoma (continued). "We recently reported that the natural product Thymoquinone (TQ) can downregulate TWIST1 and inhibit breast cancer cell migration and invasion." (PMID 27412325, 2016). "Phosphorylation of Ser 68 within Twist1 induced by p38/MAPK pathway has been characterized to be critical for its stability in breast cancer." (PMID 26959880, 2016). "Unexpectedly, we observed that BRMS1 downregulates not only TWIST1 but also Snail expression, thereby inhibiting breast cancer cell invasion." (PMID 26520789, 2015). "Twist1 can induce EMT to facilitate breast cancer cell intravasation into the circulation and the subsequent dissemination of these cells into the lungs." (PMID 26146543, 2015). "As Twist1 and Snail play an essential role in EMT as well as breast cancer metastasis, our data establish a mechanistic link between miR-129-5p, Twist1, Snail, in EMT and breast cancer metastasis." (PMID 26460733, 2015). "Some studies have reported that miR-720 impedes cell invasion and migration, and then inhibits metastasis in breast cancer by directly targeting TWIST1." (PMID 26413265, 2015). "Knockdown or overexpression of Twist1 rescued the effects of miR-129-5p depletion or overexpression on breast cancer proliferation, migration, and invasion in MCF7 and MDA-MB-231 cells." (PMID 26460733, 2015). "There was a significant inverse correlation between miR-129-5p and Twist1 or Snail expression inav breast cancer tissues." (PMID 26460733, 2015). "Twist1 promotes the EMT process, and elevated Twist1 expression is also correlated with tumor proliferation, invasion, and metastasis in a variety of solid tumors, including breast cancer, lung cancer, prostate cancer, and oral cancer." (PMID 26460733, 2015). "We also analyzed cDNA microarray data in Oncomine34 to further confirm the role of HMGA2, SALL4 and Twist1 in breast cancer pathogenesis." (PMID 25919570, 2015). "Our data demonstrated that miR-33b dramatically downregulated the expression of HMGA2, SALL4 and Twist1 in breast cancer cells to suppress cell self-renewal." (PMID 25919570, 2015). "We demonstrate that both Snail and TWIST1 are important for TGF-β1-induced breast cancer cell invasion." (PMID 26520789, 2015). "One study suggested that Snail1 activity is required for EMT initiation, whereas Twist1 is involved in the maintenance of EMT during human breast cancer progression towards metastasis." (PMID 25586771, 2015). "A potential target is the TWIST1 transcription factor, which is often overexpressed in aggressive breast cancers and is a master regulator of cellular migration through epithelial-mesenchymal transition (EMT)." (PMID 25759817, 2015). "Consistently, miR-720 suppressed tumor migration and invasion and through targeting Twist1 in breast cancer." (PMID 25760076, 2015). "Overexpression of Twist1 in breast cancer cells induces EMT and generates cells with the properties of stem cells." (PMID 25919570, 2015). "Although NCOA1 is known to promote breast cancer metastasis through working with multiple transcription factors to upregulate the expression of Twist1, ITGA5, CSF-1, SDF1 and CXCR4, the role of NCOA1 in breast tumor angiogenesis has not been investigated." (PMID 26287601, 2015). "Previous results have reported that miR-720 is also frequently decreased in breast cancer and functions as an anti-metastatic gene by downregulating TWIST1." (PMID 26413265, 2015). "Apart from let-7d, miR-29b, and miR-214, miR-580 was also reported to act as a negative regulator of Twist1 that induces EMT in breast cancer." (PMID 24598126, 2014). "Both in mouse mammary tumors and in human breast cancers, we observed elevation of Vim, Cdh2 (N-cadherin), Snai1 and Twist1 and downregulation of Cdh1 (E-cadherin) and Ocln." (PMID 25217618, 2014). "They showed that suppression of TWIST1 by siRNA in highly metastatic mammary tumor cells specifically inhibits the cells’ ability to metastasize from the mammary gland to the lung." (PMID 25238494, 2014).
breast carcinoma (continued). "Taken together, our findings suggest that the Sox2 transcriptional activity and Twist1 can serve as markers to predict invasiveness in breast cancer cells." (PMID 23815808, 2013). "The focus of this study was underpinned by the common reactivation of ZEB1, ZEB2 and TWIST1 in aggressive and undifferentiated human breast cancers, especially in the newly identified claudin-low intrinsic subtype." (PMID 22654675, 2012). "TWIST1 mRNA expression level was analyzed by quantitative real-time reverse polymerase chain reaction (RT-PCR) in 1,427 primary breast cancers." (PMID 22967435, 2012). "Downregulation of Twist1 through small interfering RNA promotes apoptosis in human breast cancer and melanoma cell lines." (PMID 22245869, 2012). "Our suggestion is supported by the fact that, in contrast to recent reports, the induction of a more mesenchymal cell phenotype increases the transcription factor mRNAs of SnaI2 and Twist1 in breast cancer cells only by a factor of 1.6 and 1.8, respectively." (PMID 23042145, 2012). "The basic helix-loop-helix transcription factor TWIST1, also promotes tumor angiogenesis and metastasis in mammary carcinoma." (PMID 23185544, 2012). "Using Gene Set Enrichment Analysis (GSEA) of genetic profiles and cytokine array analyses, we found that IL8 was specifically up-regulated by TWIST1 over-expression in the human breast epithelial cell line MCF10A as well as other breast cancer cell lines." (PMID 22891766, 2012). "Second, as we had Affymetrix U133A gene-chips data available for a subset of samples, can we reveal which biological pathways are co-expressed with TWIST1 in breast cancer?" (PMID 22967435, 2012). "More importantly, TWIST1 mRNA expression predicts, independently of the traditional prognostic factors, poor prognosis in patients with primary breast cancer." (PMID 22967435, 2012). "Several studies on function of Twist1 in breast cancer have identified an inverse correlation between Twist1 and E-cadherin expression in invasive lobular carcinomas (ILC)." (PMID 23133563, 2012). "The biological associations suggest an involvement of the tumor microenvironment in TWIST1's adverse role in breast cancer." (PMID 22967435, 2012). "Our current study shows that high TWIST1 mRNA expression is an independent marker of poor outcome in breast cancer patients." (PMID 22967435, 2012). "Subsequent molecular analyses of the hyperplastic tissue in the breast cancer mouse model revealed a strong up-regulation of TWIST1 as well as of proteolytic enzymes suggesting EMT as an underlying mechanism for early tumor cell spread." (PMID 23029563, 2012). "During malignant cancer progression, TWIST1 plays a role in the development of distant metastasis by inducing an epithelial-to-mesenchymal transition of epithelial breast cancer cells and by prompting them to enter the bloodstream." (PMID 22439624, 2012). "The obstruction of the receptor involved in invadopodia formation, platelet derived growth factor receptor (PDGFR), through its transcription factor, Twist1, prevents breast cancer metastasis." (PMID 22174624, 2011). "TWIST1 is upregulated in human breast cancer, gastric cancer, esophageal cancer, and prostate cancer." (PMID 21304978, 2011). "We quantified CK-19, MAGE-A3, HER-2, TWIST1, hTERT α+β+, and mammaglobin gene transcripts in immunomagnetically positively selected CTCs from 92 breast cancer patients, and 28 healthy individuals used as a control group." (PMID 21967632, 2011). "Increased TWIST1 expression is correlated with an increased metastatic potential in mammary carcinoma cells." (PMID 22060274, 2011). "ARTN regulated TWIST1 expression in ER-MC cells and ARTN expression was significantly correlated to TWIST1 expression in a panel of mammary carcinoma cell lines and in a cohort of patients with ER-MC." (PMID 22060274, 2011).